RNF7 (ring finger protein 7)
Description:
Catalytic component of multiple cullin-5-RING E3 ubiquitin-protein ligase complexes (ECS complexes), which mediate the ubiquitination and subsequent proteasomal degradation of target proteins. It is thereby involved in various biological processes, such as cell cycle progression, signal transduction and transcription. The functional specificity of the E3 ubiquitin-protein ligase ECS complexes depend on the variable SOCS box-containing substrate recognition component. Within ECS complexes, RNF7/RBX2 recruits the E2 ubiquitination enzyme to the complex via its RING-type and brings it into close proximity to the substrate. Catalytic subunit of various SOCS-containing ECS complexes, such as the ECS(SOCS7) complex, that regulate reelin signaling by mediating ubiquitination and degradation of DAB1 (By similarity). The ECS(SOCS2) complex mediates the ubiquitination and subsequent proteasomal degradation of phosphorylated EPOR and GHR. Promotes ubiquitination and degradation of NF1, thereby regulating Ras protein signal transduction (By similarity). As part of the ECS(ASB9) complex, catalyzes ubiquitination and degradation of CKB. The ECS(SPSB3) complex catalyzes ubiquitination of nuclear CGAS. As part of the ECS(RAB40C) complex, mediates ANKRD28 ubiquitination and degradation, thereby inhibiting protein phosphatase 6 (PP6) complex activity and focal adhesion assembly during cell migration. The ECS(ASB7) complex acts a negative regulator of H3K9me3 histone mark by mediating ubiquitination and degradation of SUV39H1. As part of some ECS complex, catalyzes 'Lys-11'-linked ubiquitination and degradation of BTRC. ECS complexes and ARIH2 collaborate in tandem to mediate ubiquitination of target proteins; ARIH2 mediating addition of the first ubiquitin on CRLs targets. As part of the ECS(LRRC58) complex, mediates CDO1 ubiquitination and degradation, regulating cysteine catabolism. Specifically catalyzes the neddylation of CUL5 via its interaction with UBE2F. Does not catalyze neddylation of other cullins (CUL1, CUL2, CUL3, CUL4A or CUL4B). May play a role in protecting cells from apoptosis induced by redox agents. [Isoform 2]: Inactive. (Microbial infection) Following infection by HIV-1 virus, catalytic component of a cullin-5-RING E3 ubiquitin-protein ligase complex (ECS complex) hijacked by the HIV-1 Vif protein, which catalyzes ubiquitination and degradation of APOBEC3F and APOBEC3G.
Synonyms: Rbx2; CKBBP1; ROC2; SAG
Tractability: PROTAC: ubiquitination databases record sites on it; its protein half-life has been measured.
Gene: Protein-coding gene on chromosome 3 (141,738,249 to 141,747,560, forward strand). Ensembl gene ENSG00000114125.
Subcellular location: Cytoplasm; Nucleus
Subcellular location (Human Protein Atlas): Nucleoplasm; Cytosol
Pathways (Reactome):
Immune System: Antigen processing: Ubiquitination & Proteasome degradation; Inactivation of CSF3 (G-CSF) signaling
Metabolism of proteins: Neddylation
Gene Ontology:
Molecular function: cullin family protein binding; NEDD8 ligase activity; protein binding; ubiquitin protein ligase activity; copper ion binding; NEDD8 transferase activity; zinc ion binding
Biological process: endoplasmic reticulum unfolded protein response; negative regulation of focal adhesion assembly; proteasome-mediated ubiquitin-dependent protein catabolic process; protein K11-linked ubiquitination; protein neddylation; negative regulation of focal adhesion disassembly; positive regulation of cell migration; post-translational protein modification; protein ubiquitination; reelin-mediated signaling pathway; regulation of neuron migration; response to redox state; ubiquitin-dependent protein catabolic process; intracellular signal transduction
Cellular component: Cul5-RING ubiquitin ligase complex; cytoplasm; cytosol; nucleoplasm; nucleus
Genetic constraint (gnomAD): Loss-of-function variants: 5 observed, 11.13 expected, observed/expected ratio (o/e) 0.45, 90% interval 0.23 to 0.94. The upper end of that interval is the gene's LOEUF score, 0.94, which puts it in group 4 of 6, group 1 being the genes least tolerant of losing a copy. Missense variants: 73 observed, 109.92 expected, observed/expected ratio (o/e) 0.66, 90% interval 0.55 to 0.81. Synonymous variants: 49 observed, 42.92 expected, observed/expected ratio (o/e) 1.14, 90% interval 0.91 to 1.45.
Homologues: Orthologues: chimpanzee RNF7 (100% identical), macaque RNF7 (100% identical), guinea pig RNF7 (96% identical), mouse Rnf7 (96% identical), rat Rnf7 (96% identical), mouse Rnf7l (94% identical), zebrafish rnf7 (92% identical), tropical clawed frog rnf7 (81% identical), Drosophila melanogaster Roc2 (73% identical), Caenorhabditis elegans rbx-2 (55% identical), pig RNF7 (52% identical). Paralogues in human: RBX1 (46% identical), ANAPC11 (27% identical).
Diseases named in the same sentence as RNF7 in open-access papers:
RNF7 is named in the same sentence as 29 diseases in open-access papers, as found by Europe PMC text mining. Sharing a sentence is not in itself a finding about the gene and the disease. The quoted sentences say what the papers report.
prostate carcinoma (7 papers, 2017 to 2025). A carcinoma that arises from epithelial cells of the prostate gland. "In addition, it was reported that RNF7 exhibits an oncogenic role in the development of prostate cancer interacting with PTEN-loss via activating the PI3K/Akt/mTOR signaling pathway." (PMID 36644576, 2023). "In line with previous finding that RNF7 knockdown sensitizes tumor cell response to radiotherapy by increasing cellular apoptosis, we corroborated that YTHDF1 or RNF7 knockdown increased DDP-induced cellular apoptosis in prostate cancer cells." (PMID 40251202, 2025). "We further performed RNF7 knockdown in prostate cancers and observed a significant inhibition of tumor cell proliferation." (PMID 40251202, 2025). "Our findings are consistent with previous studies, we showed that knockdown of YTHDF1 inhibits RNF7 expression, resulting in abnormal ROS accumulation upon DDP treatment in prostate cancer, while overexpression of RNF7 can reverse this effect." (PMID 40251202, 2025). "As expected, we overexpressed RNF7 in prostate cancer cell lines in combination with YTHDF1 knockdown, which counteracted the inhibitory effect of YTHDF1 knockdown on tumor cell proliferation." (PMID 40251202, 2025). "In prostate cancer, high RNF7 expression is known to influence tumor progression, and RNF7 knockdown enhances the sensitivity of prostate cancer cells to cisplatin." (PMID 35562668, 2022). "To determine the effect of RNF7 knockdown on prostate cancer cell proliferation, we seeded 1 × 105 cells in 12 well plates and cultured them for 7 days." (PMID 28252001, 2017). "The role of RNF7 in prostate cancer, especially in castration resistant prostate cancer (CRPC), is not yet clear." (PMID 28252001, 2017). "In this study, we silenced RNF7 by shRNA interference in two castration resistant prostate cancer (CRPC) cell lines, DU145 and PC3." (PMID 28252001, 2017). "RNF7 knockdown attenuated proliferation and enhanced sensitivity of prostate cancer cells to cisplatin treatment." (PMID 28252001, 2017). "RNF7, an apoptosis-sensitive gene, has been shown in several previous studies to play an important role in the development and progression of tumors such as prostate cancer and lung cancer." (PMID 33414811, 2020). "PSMA1, MRAS, LEP, SLC30A3, and RNF7 were found closely related with prostate cancer." (PMID 32528533, 2020). "Clonogenic survival assay was performed to detect the role of RNF7 in prostate cancer cell colony." (PMID 28252001, 2017). "In conclusion, our study demonstrated that RNF7 knockdown could suppress proliferation and inhibit tumor formation of prostate cancer cells." (PMID 28252001, 2017). "In conclusion, our study demonstrated that RNF7 knockdown inhibited prostate cancer cell proliferation and tumorigenesis, suggesting that RNF7 might be a promising target for CRPC treatment." (PMID 28252001, 2017). "So, RNF7 silencing enhanced the sensitivity of prostate cancer cell lines to cisplatin." (PMID 28252001, 2017). "RNF7 protein levels, but not transcript levels, were found to be elevated in prostate cancer cell lines, compared to that in RWPE-1." (PMID 40251202, 2025). "We demonstrated that RNF7 knockdown induced growth suppression of prostate cancer cells and inactivated ERK1/2 pathway, which suggested RNF7 might be a potential novel therapeutic target for CRPC." (PMID 28252001, 2017). "However, the role of RNF7 in prostate cancer progression is not well elucidated." (PMID 28252001, 2017). "To validate the critical role of YTHDF1/RNF7/p27 in prostate cancer, we initially assessed RNF7 expression in a prostate cancer tissue microarray and observed a positive correlation between RNF7 and YTHDF1 proteins, without detecting significant change in RNF7 mRNAs." (PMID 40251202, 2025).
lung carcinoma (6 papers, 2019 to 2025). "Based on our data, patients with lung cancers that exhibit loss of function mutations in either CUL5, RNF7, UBE2F or Elongin B that coincide with high expression of MCL1/Bcl-xL could be good candidates for treatment with CDK9i or MCL1i." (PMID 31294695, 2019).
glioma (3 papers, 2020 to 2025). A benign or malignant brain and spinal cord tumor that arises from glial cells (astrocytes, oligodendrocytes, ependymal cells). "Together, these results indicate that RNF7 expression is positively associated with clinical glioma malignant grade and negatively associated with the prognosis of patients." (PMID 36578229, 2023). "The loss/gain‐of‐function study revealed that RNF7 facilitated cell cycle progression and proliferation and suppressed apoptosis of glioma cells in vivo and in vitro." (PMID 36578229, 2023). "Here, we report the clinical relevance of RNF7 as a prognostic marker and the biological function of RNF7 in glioma." (PMID 36578229, 2023). "The effect of RNF7 on glioma progression was measured by performing CCK‐8 and apoptosis assays, cell cycle‐related experiments and animal experiments." (PMID 36578229, 2023). "In summary, our results show that RNF7 plays a key biological role in human glioma by promoting proliferation and cell cycle progression and suppressing apoptosis of glioma cells by this PI3K/AKT pathway." (PMID 36578229, 2023). "Further univariate and multivariate Cox regression analyses indicated that a high RNF7 mRNA expression level was an independent prognostic factor for poor survival of patients with glioma." (PMID 36578229, 2023). "This study shows that RNF7 can clearly promote glioma cell proliferation by facilitating cell cycle progression and inhibiting apoptosis by activating the PI3K/AKT signalling pathway." (PMID 36578229, 2023). "In this study, we found that RNF7 was overexpressed in human glioma tissue and cell lines and promoted glioma cell proliferation both in vitro and in vivo, indicating that RNF7 plays a critical role in glioma." (PMID 36578229, 2023). "Here, knockdown and overexpression experiments in vitro and in vivo indicated that RNF7 promotes glioma cell proliferation by facilitating cell cycle progression and inhibiting apoptosis." (PMID 36578229, 2023). "First, we found that RNF7 was upregulated in tumour tissue compared with normal brain tissue, especially in high‐grade glioma, and the high expression of RNF7 was significantly related to tumour size, Karnofsky Performance Scale score and a poor prognosis." (PMID 36578229, 2023). "However, the underlying mechanisms of RNF7 in glioma development remain largely unknown." (PMID 36578229, 2023). "We also found that elevated expression levels of TCEB1, TCEB2, SOCS3 or RNF7 correlate with higher glioma grades, providing new molecular parameters for glioma grading." (PMID 32931454, 2020). "Targeting the RNF7/PI3K/AKT axis may provide a new perspective on the prevention or treatment of glioma." (PMID 36578229, 2023). "Herein, our data indicated that RNF7 was highly expressed in glioma, and a high expression level of RNF7 conferred poor prognosis and could act as an independent prognostic marker for glioma." (PMID 36578229, 2023). "In addition, we examined the correlation between RNF7 mRNA levels and clinicopathological characteristics in 57 glioma specimens." (PMID 36578229, 2023). "Taken together, RNF7 might promote glioma progression via activating this PI3K/AKT signalling." (PMID 36578229, 2023). "Furthermore, follow‐up mechanistic studies indicated that RNF7 could facilitate glioma cell proliferation and cell cycle progression and inhibit apoptosis by activating the PI3K/AKT signalling pathway." (PMID 36578229, 2023). "The high‐throughput screen indicated that RNF7 might regulate glioma development." (PMID 36578229, 2023). "In addition, from a therapeutic perspective, targeting the RNF7/PI3K/AKT axis may act as a new perspective on the prevention or treatment of glioma." (PMID 36578229, 2023). "Recent studies also showed that downregulation of RNF7 leads to inactivation of the PI3K/AKT signaling pathway, which suppresses cell proliferation while inducing apoptosis in glioma." (PMID 40251202, 2025).
glioma (continued). "In the Chinese Glioma Genome Atlas (CGGA) dataset, we found that elevated expression levels of SOCS1, SOCS3, TCEB1, TCEB2 and RNF7 correlated with more advanced WHO grades (grades III and IV) of primary glioma." (PMID 32931454, 2020). "We found that primary glioma patients with higher-than-median expression levels of either SOCS1, SOCS3 or RNF7 had an unfavorable prognosis compared to those with lower-than-median expression levels (P < 0.0001)." (PMID 32931454, 2020). "Then, immunohistochemistry (IHC) was used to detect RNF7 protein levels in NBT and glioma tissues." (PMID 36578229, 2023). "The roles of RNF7, however, in glioma have not been fully elucidated." (PMID 36578229, 2023). "However, neither the function of RNF7 nor its mechanism were elucidated in glioma." (PMID 36578229, 2023). "However, the possible role of RNF7 in glioma has not been reported." (PMID 36578229, 2023).
non-small cell lung carcinoma (3 papers, 2013 to 2020). A group of at least three distinct histological types of lung cancer, including non-small cell squamous cell carcinoma, adenocarcinoma, and large cell carcinoma. "Expression of RNF7 has been found to be a prognostic marker in non-small cell lung cancer." (PMID 24299561, 2013).
fibrosis (2 papers, 2020). the formation of excess fibrous connective tissue in an organ or tissue in a reparative or reactive process. "To investigate the underlying mechanism of lnc RNF7 function on rat CF, we used ISP or Ang II to construct a fibrosis cell model on primary rat cardiac fibroblasts and then infected these cells with Lv-sh-lnc RNF7, as confirmed by real-time PCR." (PMID 31913855, 2020).
pancreatic cancer (2 papers, 2020 to 2023). "There are also relevant studies showing that RNF7 regulates ionizing radiation-induced apoptosis in pancreatic cancer." (PMID 33414811, 2020). "To confirm whether RNF7 exerts promoting effect in tumor development in vivo, we established a subcutaneous tumorigenesis model by injecting pancreatic cancer cells with stable overexpression of RNF7 or control cells into mice." (PMID 36644576, 2023). "Using multivariate Cox regression analysis, we detected eight optimal ubiquitination-related genes (RNF7, NPEPPS, NCCRP1, BRCA1, TRIM37, RNF25, CDC27, and UBE2H) and then used them to construct a risk model to predict the prognosis of pancreatic cancer patients." (PMID 33414811, 2020). "However, the underlying mechanism by which RNF7 contributes to pancreatic cancer (PC) is lacking." (PMID 36644576, 2023). "But we found that even though some genes (RNF7, NPEPPS, and NCCRP1) were down-regulated in tumor group, patients with pancreatic cancer with high expression of these genes had a worse prognosis." (PMID 33414811, 2020).
psoriasis (2 papers, 2017 to 2018). An autoimmune condition characterized by red, well-delineated plaques with silvery scales that are usually on the extensor surfaces and scalp. "We show evidence that RNF7 negatively regulates CARMA2-mediated NF-κB signaling, whereas a psoriasis-linked CARMA2 mutant escapes this negative regulation." (PMID 29194363, 2017). "It is therefore interesting to note that RNF7 is able to repress the NF-κB-inducing activity of wild type (wt) CARMA2sh, but not that of the two psoriasis-associated mutants CARMA2shE138A and CARMA2shE142G." (PMID 29194363, 2017). "Interestingly, CARMA2short (CARMA2sh) mutants associated with psoriasis susceptibility escape the negative control exerted by RNF7." (PMID 29194363, 2017). "Interestingly, the NF-κB activation produced by the psoriasis-linked mutants CARMA2shE138A and CARMA2shE142G were not affected by RNF7 expression, despite both mutants still being associated with RNF7." (PMID 29194363, 2017). "In fact, RNF7 abrogates ubiquitination of MALT1 induced by CARMA2shE138A expression, but not MALT1 ubiquitination induced by CARMA2shE142G expression, indicating that the various CARMA2 mutants associated with psoriasis so far identified can cause the disease through different molecular mechanisms." (PMID 29194363, 2017). "Interestingly, RNF7 abrogates ubiquitination of MALT1 and NEMO induced by the psoriasis-associated mutant CARMA2shE138A, but not that induced by the psoriasis-associated mutant CARMA2shE142G." (PMID 29194363, 2017).
renal cell carcinoma (2 papers, 2022 to 2025). "RNF7 overexpression is indicated in multiple human cancers, but its role in renal cell carcinoma (RCC) and the mechanisms underlying how it regulates the initiation and progression of RCC have not been explored." (PMID 35562668, 2022). "In renal cell carcinoma, RNF7 activates the JAK/STAT3 signaling pathway by inducing SOCS1 ubiquitination, leading to reduced cellular apoptosis." (PMID 40251202, 2025).
chronic hepatitis C (1 paper, 2015). "European GWAS have identified SNPs in MERTK, GLT8D2, TULP1, and RNF7 as the genetic factors responsible for liver fibrosis progression in chronic hepatitis C during the natural course." (PMID 26352693, 2015).